NF1 (neurofibromin 1)
Diseases named in the same sentence as NF1 in open-access papers (continued):
Sharing a sentence is not in itself a finding about the gene and the disease.
breast cancer (continued). "The lifetime risk of breast cancer associated with pathogenic variants in NF1 is approximately 20%, with a significant risk of developing breast cancer under the age of 50, such that it has been suggested that patients with NF1 should be referred for enhanced breast cancer screening." (PMID 34771713, 2021). "NF1 mutations are enriched in ER+ breast cancers of patients." (PMID 33842308, 2021). "Also, albeit uncommon, either BRCA1 or BRCA2 mutation has been detected in women with NF1 who develop breast cancer." (PMID 33954070, 2021). "However, when grouping samples with both AKT1-E17K and NF1 mutations, breast cancer becomes the most prevalent, corresponding to 73% of all tumors." (PMID 32858845, 2020). "The link between breast cancer susceptibility and NF1 alterations was already established." (PMID 32858845, 2020). "Furthermore, NF1-associated breast cancer was associated with poorer survival compared to breast cancer among the general population." (PMID 32014052, 2020). "The NF1 gene is included in some of the breast cancer screening genetic panels as deleterious mutations on the NF1 gene have been associated with a two to four fold increased risk of breast cancer." (PMID 30962859, 2019). "NF1 predisposes to a variety of benign and malignant tumor types, including breast cancer." (PMID 31121919, 2019). "NF1-associated breast cancers typically arise at a younger age and have the highest incidence in women under 40 years of age; women with NF1 less than 50 years of age have been recently identified to have an up to five-fold increased risk of breast cancer." (PMID 31121919, 2019). "A cross-specialty screening methodology that combines breast MRI, mammogram and ultrasound may represent a feasible strategy to screen women at high risk of breast cancer, specifically NF1 patients." (PMID 31121919, 2019). "Despite emphasis on breast cancer surveillance in women with NF1, the uptake and feasibility of high-risk screening programs in this population remains unclear." (PMID 31121919, 2019). "The patient’s breast cancer may also be linked to her diagnosis of NF1 as the association between premenopausal breast cancer and NF1 is now widely recognized." (PMID 31507634, 2019). "Interestingly, somatic mutations of the NF1 gene are reported in 27.7% of all breast carcinomas and have been implicated as potential genomic drivers in the development of breast cancer." (PMID 30962859, 2019). "In addition to the four studies included in this meta-analysis, several other cohort and epidemiological studies have suggested an association of breast cancer in young women with NF1." (PMID 30962859, 2019). "This systematic literature review and meta-analysis suggests that women with NF1 less than 50 years of age have a five-fold increased risk of breast cancer, present with more advanced disease, and may have an increased breast cancer related mortality." (PMID 30962859, 2019). "The objective of this study is to highlight the association between women with NF1 and an increased risk of breast cancer and to reinforce the importance for physician and patient education on the need for early breast cancer screening for this patient population." (PMID 30962859, 2019). "Patients whose cancers, including breast cancers, possess NF1 mutations have worse survival." (PMID 30370249, 2018). "Mutations in a tumor suppressor gene called NF1 may be an important prognostic indicator for women with breast cancer and a therapeutic target for tumors resistant to hormone therapy." (PMID 30182054, 2018). "Interestingly, one module (179 genes) associated with NF1 shallow deletion copy number status contained several genes that are considerably important in both ER+ breast cancers and endocrine resistance, including ESR1." (PMID 30182054, 2018).
breast cancer (continued). "To examine whether our Nf1-deficient rat breast cancer model was estrogen dependent, we performed ovariectomies on rats containing at least one tumor greater than 1500 mm3." (PMID 30182054, 2018). "In addition, NF1 aberrations have been linked to more adverse outcomes in other cancer types such as breast cancer and head and neck squamous cell carcinoma." (PMID 28267273, 2017). "Somatic NF1 deletions were found in almost all (59/60) of the mammary tumours studied in this mouse model, and upon subsequent examination of TCGA data, it was noted that NF1 is somatically mutated or deleted in 27.7% of human breast cancers." (PMID 28637487, 2017). "A number of breast cancer genome sequencing studies have identified NF1 as one of a number of novel, recurrently mutated genes in sporadic tumours which could potentially be targeted in a therapeutic context." (PMID 28637487, 2017). "Interestingly, we identified that mutations in PTEN and NF1 were also associated with APOBEC3 mutation enrichment in the different breast cancer subtypes, further implicating PI3K and MAPK signalling in co-regulating APOBEC3 mutagenesis in breast cancer." (PMID 27634334, 2016). "NF1 patients are also susceptible to various forms of cancers, including glioma of the optic pathway, gastrointestinal stromal tumors, rhabdomyosarcomas, leukemia, breast cancers, etc.; development of which requires a complete loss of Nf1 gene function." (PMID 27494873, 2016). "Concerning the association between NF1 and breast cancer, only a few cases have been reported." (PMID 25889501, 2015). "To date, the study with the largest cohort of NF1 individuals (n = 448) that investigated the prevalence of breast cancer, as well as other types of cancer, showed that the risk of breast cancer was significantly higher in NF1 patients younger than 50 years of age than in the general population." (PMID 25885768, 2015). "NF1 is also a risk factor for the development of breast cancer." (PMID 25885768, 2015). "The scientific data support a real association between breast cancer and NF1." (PMID 25885768, 2015). "The first report of an association between NF1 and breast cancer was published in 1972." (PMID 25885768, 2015). "Additionally, the cumulative risk of developing breast cancer at the age of 50 years was 2% in women in the general population and was 8.4% in women with NF1." (PMID 26604930, 2015). "Here, we reported two cases of NF1 associated with breast cancer." (PMID 26604930, 2015). "Interestingly, about 28% of sporadic breast cancers are missing at least one copy of the NF1 gene, either due to deletion or mutation." (PMID 25889501, 2015). "Additionally, the risk of breast cancer was nearly threefold higher in women with NF1 who were under 50 years old than in women in the general population." (PMID 26604930, 2015). "We also review the literature concerning the association between NF1 and breast cancer." (PMID 25885768, 2015). "More recently, an increased risk of breast cancer among women with NF1 has also been reported." (PMID 25026295, 2014). "In mouse model studies, Nf1+/− mice subjected to irradiation developed in-field tumours associated with NF1 such as phaeochromocytomas, as well as typical second malignant neoplasms such as sarcomas and breast cancers." (PMID 25026295, 2014). "Furthermore, we reviewed the English literature, found 63 cases showing the association between NF1 and breast cancer, and added one more case." (PMID 24876981, 2014). "Considering that breast cancer is already a common tumor in women, it would be difficult to know whether the coexistence of NF1 and breast cancer is a coincidence or a real predisposition." (PMID 24876981, 2014). "In addition, recently, literature has demonstrated an increased risk of breast cancer in women with NF1." (PMID 24876981, 2014). "The present study demonstrated an important association between NF1 and breast cancer." (PMID 24876981, 2014).
breast cancer (continued). "Women with NF1 are at risk of developing breast cancer and men also may be at risk but there is scarce data on the risk and association of NF1 with male breast cancer due to its rarity." (PMID 24565603, 2014). "NF1 has also been implicated as a breast cancer driver in a recent mouse model study." (PMID 25026295, 2014). "NF1 is deleted or mutated in 27.7% of all breast carcinomas." (PMID 25051360, 2014). "However, Güran and Safali reported a case of breast carcinoma in an NF1 patient and loss of heterozyosity of the NF1 gene in the carcinoma tissue." (PMID 24137429, 2013). "Although these are small numbers, if further work in this area confirms an increased risk of relatively early-onset breast cancer in patients with NF1, this could have implications for breast screening in this population." (PMID 16786042, 2006). "Interestingly, somatic pathogenic NF1 variants may contribute to endocrine resistance in advanced breast cancer; however, their precise clinical relevance in individuals with germline pathogenic NF1 variants remains to be fully elucidated." (PMID 41528496, 2026). "Importantly, NF1 is associated with relatively poor breast cancer survival." (PMID 31121919, 2019). "In our cohort, all cases of breast cancer were detected by breast MRI and the majority of abnormal diagnostic screens were clarified using breast MRI and/or ultrasound, providing evidence for the utility of a combinatorial high-risk screening program for NF1 patients." (PMID 31121919, 2019). "Notably, NF1 predisposes affected individuals to several types of malignant neoplasms and recently several studies have established an association between NF1 and an increased risk for breast cancer." (PMID 31121919, 2019). "The study clearly demonstrated that three individuals shared a common haplotype, including the NF1 and BRCA1 loci on chromosome 17 and speculated that the occurrence of NF1 and breast carcinoma in this family was due to the presence of two linked mutations at the NF1 and BRCA1 foci." (PMID 24137429, 2013). "The concordance of the outcomes suggests that NF1 patients achieve locoregional control rates comparable with those observed in the general breast cancer population when treated with adjuvant radiation therapy." (PMID 41487701, 2026). "Breast cancer in this cohort has a higher frequency of grade 3 and larger tumour size compared to non-NF1 breast cancers, with later presentations resulting in a poorer prognosis." (PMID 38859614, 2025). "NF1 (NM_000267.3) c.888+2T>C (GRCh37 chr17:29509685-T-C) was identified in a patient who has a personal history of early-onset breast cancer and a family history of breast, bone and prostate cancers in first- and second-degree relatives." (PMID 41300834, 2025). "The analysis also reveals mutual exclusivity between NF1 shallow deletions and mutations in MAP3K1, PIK3CA, and GATA3, which occur more commonly in luminal breast cancers." (PMID 41226361, 2025). "A woman with a known history of NF1, enlarged right breast, and pectus carinatum presented with locally advanced breast cancer of the left breast." (PMID 40691558, 2025). "Historically, uncertainty surrounded the link between an elevated breast cancer risk and NF1, with death certificates, for example, failing to show that a woman had NF1 when they died of breast cancer." (PMID 38859614, 2025). "Neurofibromatosis type 1 (NF1) is a tumor suppressor gene, and approximately 27% of breast cancers exhibit NF1 alterations." (PMID 40244377, 2025).
breast cancer (continued). "Specifically, they report that about 20% of ER+/HER2− breast cancers in the METABRIC dataset harbor a shallow NF1 deletion (−1 copy number) correlating with poorer RFS and disease-specific survival." (PMID 41226361, 2025). "National Comprehensive Cancer Network Guidelines version 3.2023 recommended to start the annual mammogram at 30 years and consider MRI as screening for breast cancer in NF1 patients." (PMID 38282102, 2024). "According to the NCCN guidelines v2.2024 (27 September 2023), germline PVs in the genes ATM, BARD1, RAD51C, RAD51D, NF1, and CHEK2 confer an absolute breast cancer risk between 17% and 40%." (PMID 38893140, 2024). "Studies on epithelial cells of NF1-related breast cancer has expanded our knowledge of their direct tumorigenic mechanisms, but there remains a gap in our understanding of the impact of NF1 on the mammary stroma." (PMID 38799507, 2024). "Earlier breast cancer screening than in the general population is recommended for females with NF1 as studies consistently show a higher incidence and at younger ages." (PMID 38686623, 2024). "Further, the in vivo loss-of-function Cas9-sgRNA screening identified NF1, TSC1, and TβRII as critical mediators in repressing inflammatory responses and breast cancer metastasis." (PMID 38997291, 2024). "Despite this clear role of NF1 in sporadic and inherited breast cancer, the molecular mechanisms of NF1-mediated breast cancer formation are still poorly understood." (PMID 38799507, 2024). "Recent breast cancer studies have highlighted the important role that NF1 dysregulation has in both NF1-related and sporadic breast cancers with the focus being on epithelial cells." (PMID 38799507, 2024). "Other “cancer drivers” in luminal BC from young patients were CDH1, NF1 and PTEN, which are classical TSG associated with breast cancer predisposition, as well as AKT, a classical BC oncogene." (PMID 39208653, 2024). "Provision of annual breast cancer surveillance for young women with NF1 (30–50 years) has also achieved high enrolment rates in a Canadian research study." (PMID 36444392, 2023). "Our patient had a germline NF1 mutation, and her ER/PR-negative HER2-positive breast cancer showed a poor response to systemic treatment involving chemotherapy, an immune checkpoint inhibitor, and PARPi." (PMID 37173992, 2023). "While the mechanism remains to be elucidated in breast cancer, prior work suggests that NF1 regulates the proliferation of neural stem cells in a PI3K‐dependent manner." (PMID 36892268, 2023). "From the age of 50 years females with NF1 should be screened for breast cancer according to the national guidelines for population screening in their country." (PMID 36684394, 2023). "The typical malignant manifestations associated with NF1 include MPNSTs, HGGs, juvenile myelomonocytic leukaemia (JMML) and breast cancer." (PMID 36684394, 2023). "Our previous preclinical modeling suggested that efficient RAS activation in ER+ NF1-depleted breast cancers can promote tumor cell survival when ER signaling is blocked by fulvestrant, and the consequent fulvestrant resistance can be inhibited by binimetinib." (PMID 37501682, 2023). "At the time of this study, breast cancer screening for women with NF1 in Australia was recommended annually from the age of 35 years, compared to 50 years of age for general population screening." (PMID 36444392, 2023). "Annual screening for breast cancer in females with NF1 is advised to start at the age of 30 years preferably by breast MRI." (PMID 36684394, 2023).
breast cancer (continued). "Metastatic HER2-positive breast cancers resistant to anti-HER2 therapies are enriched in somatic alterations that promote MEK/ERK signaling, including biallelic loss of NF1 and activating mutations of ERBB2." (PMID 36358725, 2022). "NF1 loss-of-function mutations, leading to hyperactivation of RAS, are frequently acquired in advanced breast cancer and enriched in endocrine-resistant tumors, particularly in lobular cancers." (PMID 36358725, 2022). "The subgroup of patients carrying these alterations shows a worse prognosis; alterations in NF1 and RAF1 are associated with significantly reduced breast-cancer-specific survival in multivariate analysis." (PMID 36358725, 2022). "Our models also showed good results on predicting mutations of RB1 (AUC 0.852), CDH1 (AUC 0.776), NF1 (AUC 0.768), NOTCH2 (AUC 0.740) in breast cancer." (PMID 34556802, 2021). "Recent reports have also linked NF1 with breast cancer, with several identifying the development of contralateral breast cancer in breast cancer patients with NF1." (PMID 33842116, 2021). "NF1’s involvement in breast cancer was eventually confirmed through the Cancer Genome Atlas program." (PMID 33842116, 2021). "Mean (SD) age at diagnosis for breast cancer in patients with NF1 was 46.61 (9.94) years compared with 61.71 (13.85) years in the general population (eTable 3 in the Supplement)." (PMID 33734413, 2021). "Women with NF1 also experience at least a 3.5-fold elevated mortality from breast cancer as well as worse five-year survival compared to the general population." (PMID 33842116, 2021). "Reported malignancies in the “classic” NF1 group included MPNSTs (n = 15), chronic myeloid leukemia (n = 1), rhabdomyosarcoma (n = 1), and breast cancers (n = 2), with some patients developing several malignant or non-malignant tumors." (PMID 34199217, 2021). "In this report, we examine the case of a patient with NF1 who developed contralateral breast cancer with multiple primary neoplasms four decades after her initial diagnosis of breast cancer." (PMID 33842116, 2021). "Our results identify an enrichment of mutations that promote RAS activation among metastatic HER2 + breast cancers that respond poorly to anti-HER2 therapy, with biallelic NF1 loss the most common alteration." (PMID 34795269, 2021). "Higher frequencies of mutations in neurofibromatosis (NF1), ataxia telangiectasia and Rad3 related (ATR), and breast cancer (BRCA1) genes have been reported in EGFR-mutant SCCs compared to EGFR-mutant adenocarcinomas." (PMID 34572868, 2021). "Although rare, several cases of NF1 patients with contralateral breast cancer have been mentioned in the literature." (PMID 33842116, 2021). "A few cases of NF1 patients with contralateral breast cancer have been identified in the literature, and our case highlights an NF1 patient who developed contralateral breast cancer nearly four decades after her initial breast cancer diagnosis." (PMID 33842116, 2021). "Higher incidence of breast cancer in NF1 is likewise known from the scientific literature, but its emergence in childhood is very rare." (PMID 34325699, 2021). "The field of breast cancer in patients with NF1 has seen increasing attention in the past few years." (PMID 32014052, 2020).